LAIR1 (leukocyte associated immunoglobulin like receptor 1)
Diseases named in the same sentence as LAIR1 in open-access papers (continued):
Sharing a sentence is not in itself a finding about the gene and the disease.
liver cirrhosis (5 papers, 2019 to 2022). "First, to understand if the level of LAIR-1 expression on Tc is associated with liver cirrhosis progression to HCC." (PMID 36293412, 2022). "We hypothesize that the level of the immune inhibitory receptor LAIR-1 expression on circulating Tc is associated with HCV-related liver cirrhosis progression to HCC." (PMID 36293412, 2022). "LAIR-1 expression is significantly upregulated in circulating T cytotoxic cells in HCV G4-related HCC when compared with liver cirrhosis." (PMID 36293412, 2022). "Recently, the role of LAIR-1 expression on monocytes and macrophages in the development and progression of liver cirrhosis was studied in liver biopsies and peripheral blood samples of cirrhotic patients." (PMID 33262757, 2020). "We studied the LAIR-1 expression on liver macrophages and blood monocytes related to the progression of liver cirrhosis." (PMID 31019980, 2019). "LAIR-1 expression was analyzed by immunohistochemistry on liver biopsies from 18 healthy controls and 22 patients diagnosed with liver cirrhosis." (PMID 31019980, 2019). "This represents an exclusive feature of liver cirrhosis, since blood monocytes from other chronic inflammatory pathologies showed similar or lower LAIR-1 levels compared with those of healthy controls." (PMID 31019980, 2019). "The aim of this work was to study the role of LAIR-1 expression on monocytes and macrophages in the development and/or progression of liver cirrhosis." (PMID 31019980, 2019). "Upregulated LAIR-1 expression on Tc could be a potential screening noninvasive molecular marker for chronic inflammatory HCV G4 related liver cirrhosis." (PMID 36293412, 2022). "A total of 64 patients with HCC and 37 patients with liver cirrhosis were enrolled in this case-controlled study, and their LAIR-1 expression on Tc related to the progression of liver cirrhosis was examined and compared to that of the apparently healthy control group (n = 20)." (PMID 36293412, 2022). "During liver cirrhosis progression to HCC post-HCV infection treatment, LAIR-1 overexpression is associated with Tc exhaustion, inflammation progression, and fatty acid build-up; moreover, cholesterol crystals increase due to dysfunctional clearance in the HCC microenvironment." (PMID 36293412, 2022). "The authors suggest that upregulation of collagen in the cirrhotic liver may serve to inhibit LAIR-1 expression on liver macrophages, suggesting a role for collagen-LAIR-1 interaction in liver cirrhosis." (PMID 33262757, 2020). "The presumed role of the inhibitory receptor LAIR-1 (CD305) in the inflammatory response suggests that it might contribute to the pathophysiology of chronic inflammatory diseases such as liver cirrhosis." (PMID 31019980, 2019). "The attributed role of LAIR-1 in the inflammatory process suggests that this receptor might also contribute to the pathophysiology of other chronic inflammatory diseases such as liver cirrhosis." (PMID 31019980, 2019). "Moreover, LAIR-1 expression on Tc may be one of the players involved in the progression of liver cirrhosis to HCC." (PMID 36293412, 2022). "However, the sensitivity of LAIR-1 expression as a noninvasive molecular marker in liquid biopsy is accepted for the detection of HCC progression from liver cirrhosis HCV G4-related infection, which opens the door for better screening of AFP-negative HCC transformation." (PMID 36293412, 2022). "Regarding the expression of LAIR-1% on Tc +cells and LAIR-1 MFI on Tc, it was significantly increased in the HCC group compared with that in the liver cirrhosis group (p = 0.012)." (PMID 36293412, 2022). "However, larger liver size and LN involvement showed a higher trend in LAIR-1 expression than N0 cases, suggesting LAIR-1 collusion during liver cirrhosis and HCC." (PMID 36293412, 2022).
liver cirrhosis (continued). "LAIR-1 is expressed on immune cells, including CD3+CD8+ cytotoxic T cells, in the tumor microenvironment and circulation, inhibiting immune cell activities and explaining liver cirrhosis progression to HCC." (PMID 36293412, 2022). "However, significant difference was noted between patients with HCC and patients with liver cirrhosis regarding serum insulin, presence of insulin resistance and liver function ALT, AST, GGT, AFP, serum albumin, GLR, TAG/HDL-C, and LAIR-1 expression." (PMID 36293412, 2022). "There were not significant differences in the number of LAIR-1+ macrophages related to the etiology of liver cirrhosis." (PMID 31019980, 2019). "The number of cells expressing LAIR-1 and the amount of this receptor expressed per cell (MFI, median fluorescence intensity) were analyzed by flow cytometry in blood monocytes from 20 healthy controls and 17 patients diagnosed with liver cirrhosis." (PMID 31019980, 2019). "The increased LAIR expression in blood monocytes represents an exclusive feature of liver cirrhosis, since blood monocytes from other chronic inflammatory pathologies such as RA or SLE showed similar or lower LAIR-1 levels compared with those of healthy controls." (PMID 31019980, 2019). "Moreover, to discover whether Tc contributes to liver cirrhosis progression to HCC in Egyptian patients with HCV genotype 4 (G4) after successful treatment through LAIR-1 involvement, as LAIR-1 resistance." (PMID 36293412, 2022). "Up to date, the increased expression of LAIR-1 in blood monocytes represents an exclusive event of liver cirrhosis, unlike other chronic inflammatory pathologies such as RA or SLE, in which blood monocytes showed similar or lower levels, respectively, compared with healthy controls." (PMID 31019980, 2019).
myeloid leukemia (5 papers, 2012 to 2025). A clonal proliferation of myeloid cells and their precursors in the bone marrow, peripheral blood, and spleen. "SP-D binds to Leukocyte-associated Ig-like receptor-1 (LAIR1), a receptor expressed on neutrophils and monocytes, and prevents the production of FcR-mediated ROS, in a human myeloid leukemia cell." (PMID 33542724, 2020). "The LAIR-1 gene-encoded protein may cause cell death in myeloid leukemias and has been identified as an anchor for tyrosine phosphatase." (PMID 36293412, 2022). "Furthermore, it has recently been demonstrated that LAIR-1 triggers a CREB-dependent signaling pathway that leads to myeloid leukemia development." (PMID 29958461, 2018). "In addition, Akt and NF-kB are targets for the action of LAIR1 also in primary myeloid leukemias indicating that anywhere LAIR1 is expressed, its engagement evokes a similar cellular response." (PMID 22355402, 2012).
osteosarcoma (5 papers, 2020 to 2025). A usually aggressive malignant bone-forming mesenchymal neoplasm, predominantly affecting adolescents and young adults. "Leukocyte-associated immunoglobulin-like receptor-1 overexpression decreased Glut1 and epithelial-mesenchymal transition-related molecules, thereby inhibiting osteosarcoma cell metabolism and metastasis and providing a new target for slowing osteosarcoma progression." (PMID 35720360, 2022). "LAIR-1 expression was evaluated by immunohistochemical analysis using an osteosarcoma (OS) tissue microarray." (PMID 32563267, 2020). "Also, LAIR1 has been found on osteosarcoma tumor specimens by IHC and at a variable level of expression by WB in osteosarcoma cell lines such as MG63, SAOS2, U2OS, HOS, and SJSA-1 and healthy osteoblast hFOB1.19 cells." (PMID 40563506, 2025). "Again, the reactivity by flow cytometry and the direct analysis of LAIR1-mediated signaling have not been assessed in osteosarcoma cell lines." (PMID 40563506, 2025).
acute lymphoblastic leukemia (4 papers, 2019 to 2025). Leukemia with an acute onset, characterized by the presence of lymphoblasts in the bone marrow and the peripheral blood. "LAIR1 overexpression was associated with a bad prognosis in pediatric acute lymphoblastic leukemia (ALL)." (PMID 31336593, 2019). "In Philadelphia chromosome positive B acute lymphoblastic leukemia (Ph+ B ALL), LAIR1 was observed to be highly expressed on primary blastic cells." (PMID 36555775, 2022). "Some reports have demonstrated the expression of LAIR1 in acute lymphoblastic leukemia (ALL)." (PMID 40563506, 2025).
COVID-19 (4 papers, 2021 to 2025). A disease caused by infection with severe acute respiratory syndrome coronavirus 2. "Lung macrophages associated with COVID-19 lung inflammation upregulate LAIR1 and immunoregulatory genes including HLA-E, LAPTM5, MAFB, CD68, SIRPA, and HAVCR2." (PMID 40563506, 2025). "Type I interferon autoantibodies in patients with COVID-19 are associated with poor interferon responses and increased LAIR1 abundance in leukocytes." (PMID 34429372, 2021). "Of the five proteins differentially expressed in cMs, four [transferrin receptor (TFRC), sialic acid binding Ig-like lectin 1 (SIGLEC1), Fc fragment of IgG receptor 1a (FCGR1A), and leukocyte-associated Ig-like receptor 1 (LAIR1)] were higher expressed in COVID-19+ cases." (PMID 34429372, 2021). "In COVID-19 patients, anti-LAIR1 autoantibodies have also been detected, again highly specific to severe-to-critical COVID-19." (PMID 40563506, 2025). "Serum cytokine levels and monocyte LAIR1 expressions (Mo1 and Mo2) were analyzed by luminometry and flow cytometry in symptomatic COVID-19 outpatients on PTIC treatment." (PMID 39940787, 2025). "Our analysis of 189 cell surface proteins identified the expression of LAIR1 in cMs to be elevated in patients with COVID-19 and correlated with the impaired ISG-I response." (PMID 34429372, 2021). "Indeed, among the group of 189 cell-surface proteins analyzed, LAIR1 was increased in COVID-19 patients." (PMID 40563506, 2025). "Together, these findings suggest that early evidence of type I IFN autoantibodies and increased LAIR1 expression may help distinguish severe cases of COVID-19." (PMID 34429372, 2021). "In this study, we show evidence of LAIR1 as one receptor for PTIC through an in vitro analysis of THP-1 cells polarized to M1 and in circulating Mos of symptomatic COVID-19 outpatients on treatment with an intramuscular administration of PTIC." (PMID 39940787, 2025). "Although there are still gaps in our understanding of the functions of C1q in complex microenvironments, targeting LAIR-1 will enable the development of new therapeutic strategies for many diseases, including inflammation, SLE, tumors, and hopefully COVID-19." (PMID 35562585, 2022). "LAIR1 expression is inversely correlated with ISG-I expression response in patients with COVID-19 but is not expressed in healthy controls." (PMID 34429372, 2021). "This study’s strengths are highlighted by the potential role of LAIR1 engagement by PTIC in leading in vitro M1 to M2 polarization through the downregulation of STAT1 phosphorylation and the replication of the effect in mild to moderate COVID-19 patients under treatment with PTIC." (PMID 39940787, 2025).
Autoimmunity (3 papers, 2012 to 2025). The occurrence of an immune reaction against the organism's own cells or tissues. "As a competitive inhibitor, cit C binds LAIR-1, dampening LAIR-1–mediated inhibition and potentiating autoimmunity." (PMID 41357209, 2025). "In this section, we will discuss some instances in which LAIR1 has been shown to be involved in autoimmunity and inflammatory diseases." (PMID 36555775, 2022). "It is therefore not surprising that LAIR1 has a critical role in autoimmunity, given its widespread pattern of expression and its ability to suppress cell activation in a number of hematopoietic cells." (PMID 36555775, 2022).
liver cancer (3 papers, 2022). An epithelial or non-epithelial malignant neoplasm that arises from the liver. "The current study was undertaken to understand the role of Tc cells LAIR-1 level expression in primary liver cancer from HCV G4." (PMID 36293412, 2022). "We found that LAIR1 expression was generally highly correlated with CD33 (a marker for myeloid cells) and CD4 (a marker for T cells) in most cancers except liver cancer." (PMID 36211388, 2022). "The results showed that these genes were highly expressed in liver cancer including CD80, CD44, HAVCR2, NRP1, and LAIR1." (PMID 35067176, 2022).
oral squamous cell carcinoma (3 papers, 2021 to 2022). "It is reported that the overexpression of LAIR-1 is associated with advanced grades in oral squamous cell carcinoma." (PMID 34943605, 2021).
renal cell carcinoma (3 papers, 2020 to 2024). "Jingushi found that LAIR1 was highly expressed in renal cell carcinoma (RCC) Ti-EVs compared with that in adjacent non-cancerous renal tissue." (PMID 38598014, 2024).
viral bronchiolitis (3 papers, 2019 to 2020). "We recently identified the collagen receptor leukocyte-associated immunoglobulin-like receptor (LAIR)-1 as a functional inhibitory receptor on airway-infiltrated neutrophils in viral bronchiolitis patients." (PMID 31080449, 2019). "Of note, RSV-infected LAIR-1-deficient mice present with greater neutrophilic inflammation upon inoculation with RSV, supporting the notion that agonism of LAIR-1 is a logical strategy to ameliorate the severity of viral bronchiolitis." (PMID 32726921, 2020). "We recently demonstrated that LAIR-1 is a functional inhibitory receptor on airway-infiltrated neutrophils of RSV infection-induced bronchiolitis patients in an ex-vivo setting." (PMID 31080449, 2019). "We therefore hypothesized that LAIR-1 regulates the neutrophil response in vivo during viral bronchiolitis." (PMID 31080449, 2019). "More recently, it was shown that LAIR-1 is expressed on in vivo activated human neutrophils and that LAIR-1 suppresses neutrophil extracellular trap formation by airway-infiltrated neutrophils obtained from patients with respiratory syncytial virus (RSV) bronchiolitis." (PMID 32973751, 2020).
allergic disease (2 papers, 2013 to 2025). An immune response that occurs following re-exposure to an innocuous antigen, and that requires the presence of existing antibodies against that antigen. "Thus, LAIR-2 is likely to play a pivotal regulatory role of LAIR-1 function on T cells This might be a quite general mechanism, and the role of LAIR-2 in diseases with chronic inflammation, including allergic diseases, is worth of investigations." (PMID 23691008, 2013).
Hepatic fibrosis (2 papers, 2020 to 2021). The presence of excessive fibrous connective tissue in the liver. "As extracellular matrix (ECM) collagen is a ligand of LAIR-1, the excessive deposition of which occurs in tissues in hepatic fibrosis, we analyzed the correlation between fibrosis markers (FibroScan value and AST-to-platelet ratio index [APRI] score) and LAIR-1 expression on T cells in the patients." (PMID 34398030, 2021).
liver disease (2 papers, 2021 to 2022). "The expression of LAIR1 was studied on liver macrophages and blood monocytes obtained from patients having progressive liver disease." (PMID 36555775, 2022). "Increased collagen deposition is a feature of liver disease and this makes its receptor LAIR1 more relevant." (PMID 36555775, 2022). "The relevance of LAIR-1 in liver disease is that one of its major ligands is collagen." (PMID 34398030, 2021).
lung diseases (2 papers, 2013 to 2019). "Our study, thus, underlines a key regulatory role of LAIR-1 in limiting neutrophilic inflammation in lung diseases." (PMID 31080449, 2019). "We show that LAIR-1 acts as a crucial regulator of neutrophils and is therefore a potential target for pharmacological intervention in neutrophil-driven lung diseases." (PMID 31080449, 2019). "In conclusion, the immune inhibitory receptor LAIR-1 suppresses neutrophil tissue migration and acts as a negative regulator of neutrophil-driven airway inflammation during lung diseases." (PMID 31080449, 2019). "In the current study, we investigated the role of LAIR-1 in regulating airway inflammation using two different models of neutrophil pre-dominant lung diseases." (PMID 31080449, 2019). "We, therefore, hypothesized that LAIR-1 regulates neutrophilic inflammation in lung diseases to minimize tissue injury." (PMID 31080449, 2019). "Similarly, in post-mortem lung tissue of term neonates that died of non-pulmonary disorders LAIR-1 positive cells were absent or only sporadically present." (PMID 24386309, 2013).
lymphoma (2 papers, 2024 to 2025). A malignant (clonal) proliferation of B- lymphocytes or T- lymphocytes which involves the lymph nodes, bone marrow and/or extranodal sites. "In lymphoma, LAIR1 expression by tumor-associated macrophages has been described." (PMID 39766129, 2024). "According to data from the Human Protein Atlas, these LAIR1+ cells were predominantly noncancerous, except for lymphoma, which consisted of malignant immune cells." (PMID 40591413, 2025).
RSV bronchiolitis (2 papers, 2019 to 2022). "We have recently identified LAIR-1 as an inhibitory receptor on activated airway neutrophils which limits NET formation during RSV bronchiolitis." (PMID 31080449, 2019). "We recently identified the collagen receptor LAIR-1 as functional inhibitory receptor on airway neutrophils obtained from RSV bronchiolitis patients." (PMID 31080449, 2019). "In stark contrast to fellow inhibitory receptor LAIR‐1, Allergin‐1 does not regulate neutrophilic inflammation in a mouse model of RSV bronchiolitis." (PMID 36444625, 2022). "Using a mouse model of RSV bronchiolitis, we demonstrate that LAIR-1 functions as a negative regulator of airway inflammation as LAIR-1 deficiency or administration of Lair1-Fc chimeric protein led to enhanced recruitment of neutrophils and lymphocytes." (PMID 31080449, 2019).
squamous cell carcinoma (2 papers, 2022 to 2023). A carcinoma arising from squamous epithelial cells. "To also investigate a potentially prognostic significance, we assessed the association of LAIR-1 expression with survival in the whole NSCLC discovery cohort (i.e., LUAD + LUSC+ other), as well as individually in adenocarcinoma (LUAD) and squamous cell carcinoma (LUSC) patient subgroups." (PMID 36960400, 2023). "In our study, the mean LAIR-1 tumor expression level of adenocarcinoma patients is higher than that of patients with squamous cell carcinoma (**, P = 0.003) but not the mean stromal expression (P = 0.59) in the discovery cohort." (PMID 36960400, 2023).
abscesses (1 paper, 2025). "In a model of S. aureus skin infection, Lair1 KO mice had significantly larger abscesses and areas of dermonecrosis compared to WT despite similar bacterial burdens." (PMID 41231542, 2025).
acute respiratory distress syndrome (1 paper, 2025). Progressive and life-threatening pulmonary distress in the absence of an underlying pulmonary condition, usually following major trauma or surgery. "Furthermore, LAIR1 can regulate macrophages’ recruitment to the lungs and their stimulation by polyinosinic/polycytidylic acid to mimic the acute lung injury and acute respiratory distress syndrome (ARDS) in viral pneumonia." (PMID 40563506, 2025).
Ascites (1 paper, 2022). Accumulation of fluid in the peritoneal cavity (between the layers of the peritoneum that lines the abdomen). "Moreover, the cases with ascites had higher LAIR-1 MFI on Tc expression level than those without ascites (p = 0.027); additionally, the cases with marked ascites had higher LAIR-1 MFI on Tc expression level than those with minimal ascites (p = 0.020)." (PMID 36293412, 2022).
asthma (1 paper, 2023). "Leptin, a small proline protein, and LAIR‐1 regulate ILC2s by targeting the PI3K‐AKT pathway, hence affecting the severity of asthma." (PMID 37357549, 2023).
autoimmune thyroiditis (1 paper, 2018). "In this example, highly expressed LAIR2 can out-compete LAIR1 for binding sites thereby resulting in a more activated phenotype, as evidenced by the correlation of autoimmune thyroiditis with elevated expression of LAIR2." (PMID 29931472, 2018).
breast tumour (1 paper, 2020). "Altogether, these findings suggest a potential oncogenic role for LAIR-1 expression in breast tumour cells." (PMID 33396670, 2020).